BRAF (B-Raf proto-oncogene, serine/threonine kinase)
Diseases named in the same sentence as BRAF in open-access papers (continued):
Sharing a sentence is not in itself a finding about the gene and the disease.
infection (30 papers, 2007 to 2025). The state of being infected such as from the introduction of a foreign agent such as serum, vaccine, antigenic substance or organism. "BRAF mutations have been implicated in prolonged inflammatory responses following infection, Bacillus Calmette-Guérin (BCG) vaccination, or tobacco exposure." (PMID 39958088, 2025). "In patients with mutation data, the factors significantly associated with death from infection versus all other deaths were 11q deletion (47/162 [29%] versus 40/209 [19%], P = 0.03) and mutations of the BRAF, FBXW7, NRAS and XPO1 genes." (PMID 33580200, 2021). "Multivariate analysis in these 400 patients showed that the factors most significantly associated with death from infection were 11q deletion and mutations of the BRAF, NRAS and XPO1 genes." (PMID 33580200, 2021). "Of the 30 BRAF-mutated patients in the trial 19 (63%) died of infection, nine of other causes and two survived." (PMID 33580200, 2021). "If validated in other studies, risk of infection should be considered when applying corticosteroids in combination with BRAF inhibitors, in particular vemurafenib." (PMID 25897843, 2015). "In the current study, the extent to which concomitant use of corticosteroids in BRAF inhibitor treated patients affects lymphocyte counts and predisposes to infection was investigated." (PMID 25897843, 2015). "To further compare the effects of shCRAF alone versus shCRAF plus shBRAF on cell growth and ERK signaling, we reduced the multiplicity of infection in transduction to achieve less potent knockdown of BRAF and CRAF in ST8814 and S462 cells." (PMID 41023593, 2025). "Mutant BRAF inhibitors have been shown to activate this MAPK kinase cascade in wild-type BRAF cells, which is also activated by EV-A71 infection." (PMID 36145288, 2022). "Up-modulation was specific for NAMPT, while the other three NBEs, i.e., NAPRT, NMRK1, and QPRT, were unaffected by infection with BRAF V600E (heatmaps on the right)." (PMID 35272691, 2022). "In addition, the inhibition of Ras, which is upstream from BRAF, had only a mild inhibitory effect on the infection of EV1 and CVB3 when a Ras inhibitor, Salirasib, was tested." (PMID 37436162, 2023). "Interestingly, we observed a reduction in infection (measured using a viral YFP reporter) when the cells were co-treated with BRAF and MEK inhibitors." (PMID 38201278, 2023). "In the univariate analysis in this subset of 400 patients, 11q deletion was significantly associated with death from infection versus deaths not due to infection, along with mutations of the BRAF, FBXW7, NRAS and XPO1 genes." (PMID 33580200, 2021). "But we are not aware of any studies, like that cited above for the NRAS gene, which might cast light on the possible mechanisms leading to a susceptibility to fatal infections in patients with a BRAF mutation, nor in those with an FBXW7 or XPO1 mutation." (PMID 33580200, 2021). "The BRAF inhibitor vemurafenib is effective in HCL, but its use in first-line treatment is restricted to select clinical situations (e.g. active infection)." (PMID 36494600, 2023). "Specifically, the expression levels of KRAS and BRAF, upstream components of the MAPK/ERK pathway, were upregulated at the early stage (3 and 6 h) of the infection." (PMID 33425779, 2020). "We also evaluated the effect of vemurafenib downstream from BRAF by studying ERK signaling during EV1 infection with or without vemurafenib." (PMID 37436162, 2023). "On the other hand, our results demonstrated that another BRAF inhibitor, sorafenib, did not inhibit the infection of EV1 and CVB3." (PMID 37436162, 2023). "Among the panel of 21 genes commonly mutated in CLL, univariate analysis showed that mutations of BRAF, FBXW7, NRAS and XPO1 were significantly associated with death from infection versus deaths not due to infection." (PMID 33580200, 2021).
colorectal (27 papers, 2006 to 2025). "Accumulation of molecular alterations, including EGFR overexpression and mutations in KRAS and BRAF, contribute to colorectal carcinogenesis." (PMID 23459231, 2013). "Thus, the frequency of alterations in different genes was fairly similar comparing colonic and rectal origin, with the exception of BRAF mutations, which were significantly more frequent in colonic NEC (P = 8.0 × 10−5)." (PMID 34647903, 2021). "In the literature, BRAF mutations are reported in about 4% of lung SCC and in 10% of lung ADC." (PMID 28619094, 2017). "Conventional chemotherapy, particularly pemetrexed/platinum-based first-line therapy, may be considered as an important treatment of choice for patients unable to receive the combination of dabrafenib and trametinib yet harboring metastatic BRAF V600E-mutated lung ADC." (PMID 31234388, 2019). "Our results show that BRAF, KRAS and PIK3CA mutations occur prior to malignant transformation demonstrating that these oncogenic alterations are primary genetic events in colorectal carcinogenesis." (PMID 18782444, 2008). "Overall survival (OS) for Stage IV lung ADC at initial diagnosis were analyzed in patients with BRAF V600E or with undetected mutation (no driver mutation/fusion detected in BRAF, EGFR, KRAS, ALK, ROS1, RET, HER2, or MET genes)." (PMID 31234388, 2019). "It has been proposed that colorectal SRCC consists of two subtypes, in which the MSI+/CIMP+/BRAF+/CD3+/PD-L1+ hypermethylated genotype is more common in the proximal colon, and may represent the potential candidate for immunotherapy." (PMID 34381313, 2021). "In conclusion, our results show that mutations of BRAF, KRAS and PIK3CA occur in non-malignant lesions of colorectum demonstrating that these oncogenic alterations are primary genetic events in colorectal carcinogenesis." (PMID 18782444, 2008).
benign tumors (21 papers, 2013 to 2025). "Finally, it should be borne in mind that BRAF mutations on nodules with inconclusive cytology results from FNA are rarely found in benign neoplasms, since 99% of nodules with BRAF mutations are positive for malignancy on final histopathology." (PMID 38255638, 2023). "In benign neoplasms like MA, several authors have noted that testing for the BRAF V600E mutation may be a valuable tool for the diagnosis." (PMID 35198098, 2022). "Increased tumor suppressor p16 (INK4α) expression in these BRAF V600E-mutated indolent or benign neoplasms may partly explain this phenomenon, which causes cell cycle arrest and senescence." (PMID 30111351, 2018). "The specific BRAF gene mutation V600E has been reported in over half of all cutaneous melanomas and papillary thyroid carcinomas, as well as in a number of blood cancers including hairy cell leukemia; it is also present in indolent and benign tumors such as melanocytic nevus." (PMID 35198098, 2022). "It was reported that BRAF V600E induces senescence via regulation of p16 (INK4α) in some indolent or benign neoplasms." (PMID 30111351, 2018). "In situ hybridization with probes corresponding to the BRAF locus and the chromosome 7 centromere was interpretable in 27 of these 33 BRAF mutant benign tumors (81.2 %), and chromosome 7 was diploid in all cases." (PMID 26141748, 2015). "The CRNDEP level was significantly elevated in highly aggressive tumors (hgOvCa) compared to benign neoplasms (BOTS without the BRAF V600E mutation)." (PMID 39062774, 2024). "In the second blind-label cohort, overall concordance was consistent in 85.7% of cases whereas 10.7% of cases had a histologic diagnosis of malignancy without the BRAF mutation, and 3.6% had a histologic diagnosis of a benign neoplasm and the BRAF mutation." (PMID 35711804, 2022). "Among 41 nodules (57.8%) identified with neither RAS, BRAF V600E, nor TERT promoter variants, 17 were benign tumors, 1 was NIFTP, 14 were CPTCs, and 9 were IEFVPTCs." (PMID 38758552, 2024). "BRAF mutations were present in four MBTs but absent in MOC and benign tumors." (PMID 39040449, 2024).
colon (20 papers, 2012 to 2025). "Conversely, in LOCRC, right colon tumors show BRAF mutations." (PMID 37444619, 2023). "Right colon tumors have a higher rate of BRAF mutations than left ones." (PMID 37444619, 2023). "This is especially relevant for MSI mCRC, RAS/BRAF-wild-type GI tumors (particularly in pancreatic cancer), refractory or rare histologies, and cases lacking other actionable drivers." (PMID 41153346, 2025). "NRAS mutation was significantly more frequent in patients > 64 years of age, BRAF mutation in women, and NRAS/BRAF mutations in right colon tumors." (PMID 37886935, 2023). "The low BRAF mutation frequency compared to our present data may be due to fewer colon NECs; however, primary sites were not specified." (PMID 34647903, 2021).
hematologic malignancies (13 papers, 2015 to 2026). "To identify any additional cases of BRAF V600E-mutant AML, we queried our in-house molecular database from 2018 to 2023 for BRAF V600E-mutant hematologic malignancies." (PMID 39596583, 2024). "Although three RAF kinases (ARAF, BRAF, and CRAF) play a physiological role in mammalian cells, BRAF is the most frequently altered kinase detected in a wide range of solid tumors and a subset of hematological malignancies." (PMID 35955671, 2022).
genetic disorders (11 papers, 2016 to 2025). "Collectively, these results indicate that the reactive astrogliosis induced by overactivation of astrocytic ERK signaling could be a neuropathological mechanism of BRAF-linked genetic disorders." (PMID 39964758, 2025). "In our study, as in other Asian population, ALM was the most common type of invasive AM, but unlike other studies due to low prevalence of BRAF mutation in our study the genetic disorder in our population seems to be something else, and more studies are needed for a more accurate conclusion." (PMID 34567185, 2021).
neurological diseases (7 papers, 2019 to 2025). "For some somatic variants, it may even be possible to target the affected pathway itself, as examples such as BRAF or STAT3 inhibitors for other autoimmune and neurological diseases illustrate." (PMID 30541027, 2019).
endocrinopathies (4 papers, 2021 to 2025). "AVP-D was noted in a significant proportion of patients with ECD accompanied by a large burden of other endocrinopathies, more hypotonic urine despite vasopressin therapy, the absence of posterior pituitary bright spots, and pathogenic variants in BRAF V600E compared to those without AVP-D." (PMID 40075671, 2025).
Head and neck tumors (4 papers, 2012 to 2025). "Head and neck tumors present mutations in KRAS and BRAF, but in very low frequencies, with 6% of the patients carrying a mutation in KRAS and 3% in BRAF." (PMID 23207070, 2012).
hematologic cancers (4 papers, 2015 to 2024). "Several specific pro-oncogenic mutations of BRAF have since been identified and implicated in the development of a variety of solid and hematopoietic neoplasms." (PMID 28903326, 2017). "Mutation of the BRAF gene is rare in human common hematopoietic cancers including Non-Hodgkin’s lymphoma, multiple myeloma and acute and chronic leukemia of lymphoid and myeloid origins." (PMID 29061943, 2015). "Considering the RAS mutational frequencies of these precursor lesions (according to our data almost one third of cases with RAS mutations), this may result in significant numbers of patients at risk for the development of treatment-requiring hematological cancers on BRAF inhibition." (PMID 33042833, 2020). "This absence of BRAF mutations in canine hematopoietic cancers may reflect the fact that dogs do not develop diseases that are the counterpart of human LCH or HCL, or perhaps that the MAPK pathway is activated by different molecular mechanisms such as alterations of RAS or receptor tyrosine kinases." (PMID 29061943, 2015).
immune dysfunction (3 papers, 2020 to 2023). "First, more patients should be collected in the future to expand the sample size, which is conducive to a deeper understanding of the mechanisms of BRAF mutated SKCM and immune dysfunction." (PMID 36531226, 2022).
cardiac disease (2 papers, 2016 to 2023). "Patients with MAP2K1 variants have a lower frequency of cardiac disease than those with MAP2K2 (64%) and BRAF variants (72%)." (PMID 38136934, 2023). "In summary, human engineered cardiac tissues created from BRAF mutant cells recapitulated, for the first time, key aspects of the HCM phenotype, offering a new in vitro model for studying intrinsic mechanisms and screening new therapeutic approaches for this lethal form of heart disease." (PMID 26784941, 2016).
retinopathy (2 papers, 2017 to 2023). "However, in one small study, addition of the pan-RAF inhibitor RAF265 or the selective BRAF inhibitor encorafenib to the MEK inhibitor binimetinib did not appear to influence the incidence of retinopathy." (PMID 28646893, 2017).
brain disease (1 paper, 2019). "Among patients enrolled in Cohort A, those with treatment-naïve brain disease achieved a 56% ORR while it was 16% in BRAF mutant patients pre-treated with BRAF and MEK inhibitors." (PMID 31623643, 2019).
hepatobiliary disorder (1 paper, 2016). A non-neoplastic or neoplastic disorder that affects the liver, bile ducts, and gallbladder. "Ipilimumab (IPI), an anti-CTLA-4 antibody, and vemurafenib (VEM), a BRAF inhibitor, have distinct mechanisms of action and shared toxicities (e.g., skin, gastrointestinal [GI] and hepatobiliary disorders) that may preclude concomitant administration." (PMID 27532019, 2016).
neurodegenerative disease (1 paper, 2018). A disorder of the central nervous system characterized by gradual and progressive loss of neural tissue and neurologic function. "Interestingly, researchers proved that embryonic mutations of the BRAF gene in erythro-myeloid progenitors could cause the neurodegenerative disease after birth and induced the up-regulation of neurodegenerative markers in mouse." (PMID 30250269, 2018).
BRAF also shares sentences with these, for which no sentence is quoted: mucosal (25 papers); superficial spreading melanoma (22); head and neck cancer (9); diabetes insipidus (7); diffuse leptomeningeal glioneuronal tumor (7); kidney cancer (7); breast tumors (6); depression (6); subependymal giant cell astrocytoma (6); clear cell sarcoma (5); lentigo maligna melanoma (5); oesophageal cancer (5); anaplastic astrocytoma (4); Blood Cancer (4); breast invasive ductal carcinoma (4); cardiovascular disease (4); clear cell renal carcinoma (4); gastric adenocarcinoma (4); liposarcoma (4); Merkel cell carcinoma (4); myeloproliferative neoplasm (4); adenoid cystic carcinoma (3); adenomatoid odontogenic tumor (3); breast adenocarcinoma (3); cervical squamous cell carcinoma (3); choroidal melanoma (3); colonic polyp (3); endometrioid carcinoma (3); gangliocytoma (3); hemophagocytic lymphohistiocytosis (3).
A further 374 diseases each share a sentence with BRAF in 3 papers or fewer.